ATM (ATM serine/threonine kinase)
Diseases named in the same sentence as ATM in open-access papers (continued):
Sharing a sentence is not in itself a finding about the gene and the disease.
tumor (continued). "Genetic silencing of ATM in tumor cells promotes radiation-induced T1IFN-mediated antitumoral immune responses." (PMID 38376927, 2024). "These tumor biopsies showed upregulation of p-Rad50, a marker of ATM pathway activation, after treatment with ceralasertib, as well as an increase in the number of γH2AX-positive cells." (PMID 37934611, 2024). "For the 11 patients with HRD tumours, 2 patients had biallelic mutations (ATM and BRCA1 – both with PR), 7 patients had tumours with monoallelic HRD mutations, and 2 were unable to be determined." (PMID 38135713, 2024). "We found durable clinical benefit in diverse tumor types, with evidence suggesting multiple potential biomarkers of response to ATRi, including loss of ARID1A, genomic instability, ATM/G1 pathway abnormalities, and high tumor inflammation." (PMID 37934611, 2024). "For instance, inhibiting the DNA damage response (DDR) kinase ATM has recently been shown to inhibit myofibroblastic features, increase immune infiltration and sensitize to immune checkpoint therapy in subcutaneous tumor models." (PMID 38937629, 2024). "The application of ATM inhibitors to tumor cells blocks ATM signaling in tumor cells, leading to the inability to activate the G1/S cell cycle checkpoint and massive tumor cell death." (PMID 37305685, 2023). "It is suggested that the combination of a WEE1 inhibitor and an ATR/ATM inhibitor can enhance the anti-tumor efficacy in insensitive tumor cells." (PMID 37305685, 2023). "In an early clinical first-in-human study of another ATR inhibitor, RP-3500, similar modest monotherapy responses were observed in patients with ATM-mutant tumours." (PMID 37627223, 2023). "Chemical suppression by CP466722 or ATM knockout by siRNA effectively inhibited epithelial–mesenchymal transformation and tumor metastasis in cisplatin-resistant lung cancer cells and mouse models." (PMID 37109350, 2023). "In contrast to the data distribution of the APC gene before SMOTE sampling, the original data distribution of sequences from the ATM gene were relatively balanced as the tumor sequences comprised of 53% of the total data, and normal DNA sequences made up 47%." (PMID 36959534, 2023). "Related studies have shown that the DNA damage repair mechanism in tumor cells is extremely active, and a series of DNA damage repair-related proteins (ATM, DNA-PKcs, and Rad51) are involved in the regulation of tumor radiation resistance." (PMID 36908704, 2023). "We also explored the correlation between ATM and LP-284 response in a pair of non-tumor fibroblast cells with well-characterized ATM status." (PMID 37306526, 2023). "In this study we reveal Gal-9 upregulation via the STING-IFNβ pathway as a factor that limits the anti-tumor efficacy of ATM inhibition." (PMID 36778120, 2023). "EPCAM+, EPCAM− and EPCAM−Rhoj-KO tumour cells similarly increased the level of phosphorylated ATM/ATR substrates after cisplatin/5FU administration, showing that RHOJ does not control ATM and ATR activation after chemotherapy." (PMID 36949199, 2023). "The mutation landscape of HRR-related genes revealed several possible recurrent hotspot driver mutations in ARID1A, ATRX, ATM, and BRCA1/2, including R1989* in ARID1A, which was carried by over 30 tumor patients." (PMID 37264024, 2023). "53BP1 knockdown inhibited apoptosis induced by icotinib hydrochloride and the expression of proteins in ATM pathways, while inducing tumor proliferation." (PMID 39524544, 2023).
tumor (continued). "M3541 had high selectivity and showed more significant antitumor activity in ATM wild-type tumor cell lines, suggesting that its inhibitory effect depended on the normal function of ATM." (PMID 37109350, 2023). "These active ATM monomers coordinate the DNA repair process allowing tumor cells to evade cisplatin-induced DNA damage." (PMID 38203596, 2023). "Hsa_circ_0001546 can bind to miR-421 and thereby reverse mir-421-induced ATM down-regulation and tumor progression." (PMID 39524544, 2023). "The inhibition of ATM can increase DNA damage and activate the interferon response, thus modulating the tumor immune microenvironment (TIME) and the efficacy of ICB therapy." (PMID 37174688, 2023). "Here, we demonstrate that STAG2 knockout in multiple tumor cell lines resulted in hypersensitivity to ATM inhibitors, which is consistent with our screening data." (PMID 37985839, 2023). "Contrarily, a pathogenic CHEK2 variant was detected in a patient with a GI-negative tumor, while a patient’s tumor with an inconclusive GI status harbored a likely pathogenic FANCL variant and a splice variant in ATM." (PMID 38067228, 2023). "Here, we demonstrated that tumor cell lines with STAG2 defect are hypersensitive to ATM inhibitors as well as other DNA damage response‐related stimuli (e.g., irradiation, camptothecin, and cisplatin)." (PMID 37985839, 2023). "Among the complex tumor spheroids evaluated in this study, synergistic activities were frequently observed when the ATM inhibitor AZD-1390 was combined with topotecan or trabectedin." (PMID 37637936, 2023). "It is noteworthy that ATM is often considered a major tumor suppressor because of its ability to induce cell cycle arrest." (PMID 37081847, 2023). "In a study of patients with tumor CGP-identified mutations in moderate risk breast and ovarian CSGs (ATM, BRIP1, CHEK2, PALB2, RAD51C, and RAD51D), 24% of patients with germline variants would not have met criteria for germline testing." (PMID 37568048, 2023). "Mechanistically, ATM inhibition greatly upregulated Gal-9 expression and secretion in a variety of human and murine tumor cells via the cGAS-STING-interferon β (IFNβ) innate immune pathway." (PMID 36778120, 2023). "The ATM gene is related to proteins that act as tumor suppressors and are included in the DNA damage response after the generation of DNA DSBs." (PMID 38021491, 2023). "Our study focused on the pathogenic mutations of ATM and ATR, as both genes are from the PIKK family that is critically involved in DNA damage repair in normal cells as well as tumor cells." (PMID 38041093, 2023). "In this study, we demonstrate that Gal-9 is induced by ATM inhibition through cGAS-STING-IFNβ pathway in a variety of tumor cells." (PMID 36778120, 2023). "We demonstrate that Gal-9 expression can be increased by tumor cell-intrinsic IFNβ in response to ATM inhibition in a STING-dependent manner." (PMID 36778120, 2023).
tumor (continued). "Tumors with alterations in ATM or ATR (28.9%) displayed co‐occurring copy loss of both genes, with one tumor carrying HD of both genes." (PMID 35229492, 2022). "More importantly, it ubiquitinates ATM for degradation to overcome oncogene-induced senescence, thereby playing an important role in tumor initiation." (PMID 35379802, 2022). "The first-in-human Phase I dose-escalation trial showed elimusertib was well tolerated with clinical evidence of anti-tumor activity in patients with advanced cancers with ATM aberrations." (PMID 35458687, 2022). "We found that myofibroblast ATM shRNA knockdown similarly suppressed intratumoral myoCAF accumulation and reduced tumor size in this model." (PMID 36353752, 2022). "It is worth noting that Irofulven (MGI-114), a new cytotoxic anticancer drug with DNA damaging and MAPK activating properties, can also promote tumour cell apoptosis via ATM/CHK2 activation in the presence of BRCA1." (PMID 35801728, 2022). "Combining oncogene targeted therapies with ATM inhibitors thus eradicates residual tumor cells that would otherwise survive treatment, leading to more penetrant and durable therapeutic responses in cellular and animal models." (PMID 35353542, 2022). "Based on the key role ATM signaling was playing in the regulation of ER stress signaling and tumor cell viability, we defined the localization of activated ATM, caused by exposure to GZ17-6.02." (PMID 36408163, 2022). "We made the interesting observation in MSS CRC with high TMB that these tumours are defined by nonsynonymous variants affecting genes of the HRR pathway, commonly ATM, but also others." (PMID 35740599, 2022). "Compared to prior studies in other tumor cell types such as pancreatic, liver, or colorectal, we observed significantly greater activation of ATM and the AMPK (p < 0.05)." (PMID 36408163, 2022). "Comparing tumor to germline genotyping, all germline small variants in BRCA genes were also detected in tumors, while one small variant in the ATM gene was missed (ATM: c.5932G > T p.(Glu1978*)." (PMID 35326583, 2022). "In our cohort, a comprehensive tumor profile including homologous recombination genes (i.e., ATM, PALB2, RAD50, RAD51, RAD51B, RAD51C, RAD51D...) was performed for 100 cases, finding pathogenic alterations in four tumor samples, as previously reported." (PMID 35406410, 2022). "While ATM inhibitors can be given with low systemic side effects, modern radiotherapy localizes treatment to the tumor with tight margins." (PMID 35477555, 2022). "We first determined how blockage of ATM‐associated DNA damage affects MAPK, and mTOR signaling pathways during citrate‐mediated tumor cell senescence." (PMID 34747157, 2022). "In 5 of 5 cases, p-ATM staining was increased in tumors progressing on treatment with erlotinib relative to matched pre-treatment tumor samples." (PMID 35353542, 2022). "Various publications reported a downregulation of genes with a potential tumor-suppressive function in DNA repair, with ATM being one of the crucial and most thoroughly studied." (PMID 36139600, 2022). "Together, these data show that ATM can be targeted to suppress intratumoral myoCAF accumulation, resulting in reduced tumor growth." (PMID 36353752, 2022). "In vitro and in vivo studies have confirmed that quercetin can specifically inhibit ATM activation and ATM-mediated phosphorylation of downstream targets, leading to tumor radiosensitization." (PMID 36036010, 2022). "Our results provide evidence that the novel ATM promoter is tumor specific and has robust expression capability that is similar to the CB promoter both in vitro and in vivo." (PMID 35615262, 2022).
tumor (continued). "Correlation analysis (using low expression vs high expression as a discriminator) revealed a significant association of ATM low and HER2 high status with several clinicopathological variables such as high tumour grade, late disease stage and tumour shape." (PMID 36056635, 2022). "Initial histopathologic tumor grade was indirectly associated with TMEM173 (STING), DNA-repair (ATM, POLD4) and hypoxia related genes." (PMID 35158950, 2022). "Knock down of eIF2α, Beclin1 or ATG5 also reduced tumor cell death to a similar extent as did over-expression of FLIP-s whereas knock down of ATM less effective." (PMID 36408163, 2022). "Among the 60 patients’ USC, 22 (36.7%) carried tumor HRR gene mutations (tHRRmt), with ATM, BRCA1, and BRCA2 being the most frequently mutated genes." (PMID 36428992, 2022). "Tumor cells (HeLa and SiHa) also exhibit reduced colony formation and anchorage-independent growth potential upon ATM and CHEK2 silencing when compared to cells expressing only scrambled shRNA." (PMID 35745491, 2022). "The tumour suppressor complex BRCA1-BARD1 phosphorylated by ATM facilitates DNA end resection and interacts with PALB2, which in turn promotes the recruitment of BRCA2." (PMID 35681784, 2022). "In order to express the B8R protein only in tumor cells, we synthesized a new telomerase-based, tumor-cell-specific promoter, termed ATM, based on literature regarding sequence alterations that enhance promoter activity." (PMID 35615262, 2022). "Here, we review the molecular features and hereditary tumor risk associated with several moderate-penetrance genes in EOC that are involved in the homologous recombination repair pathway, i.e., ATM, BRIP1, NBN, PALB2, and RAD51C/D." (PMID 36233090, 2022). "Existing studies of PARP inhibition in NB have largely established its efficacy in specific tumor types, including those that amplify or overexpress MYCN, as well as those with 11q deletion and/or low ataxia-telangiectasia mutated (ATM) expression." (PMID 36227363, 2022). "Targeting fibroblast ATM in vivo suppressed myoCAF-rich tumor growth, promoted intratumoral CD8 T-cell infiltration, and potentiated the response to anti–PD-1 blockade and antitumor vaccination." (PMID 36353752, 2022). "ATM-dependent signaling in tumor cells can also increase resistance to radiotherapy and chemoresistance." (PMID 35872888, 2022). "We initially profiled the expression pattern of ERBB2 and ATM mRNA levels in a panel of different normal and tumour tissues with bioinformatics analyses using the TCGA database (Cohort one)." (PMID 36056635, 2022). "Together, the demonstration that ATM inhibition potentiates tumor responses to oncogene targeted therapies is well positioned for near term clinical development." (PMID 35353542, 2022). "Since ATM serves as an apical modulator of DSBs, the administration of ATM inhibitors can effectively increase the radiosensitivity of tumor cells." (PMID 36230796, 2022). "We combined all these features to create a potent promoter that is tumor-cell-specific (termed the ATM promoter)." (PMID 35615262, 2022). "Previous results from our and other groups suggested that induction of DDR featuring ATM/ATR pathway activation was a prominent characteristic of the CX-5461 actions in tumor cell lines and in cardiovascular cells." (PMID 36386132, 2022). "We next explored the potential causative relationships and interactions among ATM‐associated DNA damage, MAPK and mTOR signaling pathways in the process of tumor cell senescence mediated by citrate." (PMID 34747157, 2022).
tumor (continued). "Since Chk2 is a downstream kinase of ATM, inhibition of the ATM/Chk2 axis in ARID1A deficient cells led to replication stress, increased tumor-infiltrating lymphocytes, and a STING-mediated innate immune response resulting in longer patient survival." (PMID 36123603, 2022). "The authors also reported that in patients with NSCLC who underwent comprehensive tumor genome profiling, STK11 and ATM mutations were significantly enriched in tumors harboring G12C, G12A and G12V." (PMID 36348317, 2022). "In vivo, xenograft tumor model was established in nude mice to study the effect of HMGB1 on radioresistance via PI3K/AKT/ATM Signaling Pathway." (PMID 36260180, 2022). "Growth curves indicate that the tumor-derived cell lines expressing different shRNAs against ATM and CHEK2 had their proliferation potential dramatically reduced, but that silencing of these genes did not affect the proliferation of PHK." (PMID 35745491, 2022). "Whereas ATM inhibition alone had little effect on tumor growth, EGFR inhibitor monotherapy suppressed the growth of tumors before eventually giving rise to resistance outgrowth." (PMID 35353542, 2022). "In another study, tumor immunogenicity was evaluated after the pharmacological inhibition of ATM following PD-L1/PD-1 checkpoint inhibition." (PMID 35572596, 2022). "It has been suggested that ATM's role as tumour suppressor gene altered to be tumour promoter in HER2‐positive tumours." (PMID 36056635, 2022). "Investigating the protein expression of HER2 and ATM together, we found that tumours with HER2 high/ATM low had the worst OS and DFS compared with HER2 high/ATM high, HER2 low/ATM low, or high." (PMID 36056635, 2022). "Four carriers of germline mutations had additional somatic DDR mutations in the primary tumor: ERCC4; BRCA1, ATM, FANCD2, and MLH1; BRCA1; and BRCA2, RAD50, and ATR." (PMID 36446793, 2022). "On the other hand, CHEK2 and ATM carriers primarily develop ER-positive BCs, and the proportion of ER-positive tumours increases with age." (PMID 36162851, 2022). "We constructed a rAAV with the ATM promoter to express the VV B8R gene specifically in tumor cells and activate VV-specific memory T cells to antagonize cancer growth and eliminate tumors." (PMID 35615262, 2022). "Elevated ATM or ATR signaling leads to an increase in genes that suppress the tumor p21 and p27, resulting in the induction of cell cycle arrest." (PMID 35222644, 2022). "In this view, ATM higher expression in responder patients seems controversial, because it would lead to a more HR-proficient tumor cell profile in terms of DDRR response." (PMID 36110934, 2022). "Nonetheless, recent studies have shown that ATM inhibitors can promote response to checkpoint immunotherapy through cGAS/STING signaling in tumor cells, resulting in an enhanced interferon I response and increased immunogenicity." (PMID 36353752, 2022). "For ATM, the carrier probabilities for ER-negative tumours are reduced relative to previous estimates, reflecting the stronger association with ER-positive disease." (PMID 36162851, 2022). "A previous study has demonstrated that another miRNA, miR-101, downregulates the expression of both DNA-PKcs and another protein kinase, ATM, and that upregulation of miR-101 sensitizes the tumor cells to radiation." (PMID 35563814, 2022). "PTEN and ATM are already part of clinically established tumor sequencing panels and results should find access to therapeutic decisions." (PMID 35477555, 2022). "Phosphorylated ATM was identified as a driving factor of cytokine production that can increase tumor cell-derived levels of CCL5, CXCL9, CXCL10, and IL16, leading to increased CD8+ CTL infiltration." (PMID 36071479, 2022). "ATM activation is vitally important for tumor cell-derived small extracellular vesicles (sEV) to effectively induce Tregs." (PMID 36071479, 2022).